NDUFAF4 (NADH:ubiquinone oxidoreductase complex assembly factor 4)
Description:
Involved in the assembly of mitochondrial NADH:ubiquinone oxidoreductase complex (complex I). May be involved in cell proliferation and survival of hormone-dependent tumor cells. May be a regulator of breast tumor cell invasion.
Synonyms: C6orf66; HRPAP20; HSPC125; My013; bA22L21.1; MC1DN15
Tractability: Small molecule: an approved drug acts on it. PROTAC: ubiquitination databases record sites on it; its protein half-life has been measured.
Target class: Enzyme; Oxidoreductase
Gene: Protein-coding gene on chromosome 6 (96,889,313 to 96,897,894, reverse strand). Ensembl gene ENSG00000123545.
Subcellular location: Mitochondrion; Membrane
Subcellular location (Human Protein Atlas): Mitochondria; Cytosol; Nucleoplasm
Pathways (Reactome):
Metabolism: Complex I biogenesis
Gene Ontology:
Molecular function: protein binding
Biological process: defense response to virus; mitochondrial respiratory chain complex I assembly
Cellular component: mitochondrial membrane; mitochondrion; mitochondrial inner membrane; membrane
Genetic constraint (gnomAD): Loss-of-function variants: 7 observed, 13.67 expected, observed/expected ratio (o/e) 0.51, 90% interval 0.29 to 0.96. The upper end of that interval is the gene's LOEUF score, 0.96, which puts it in group 4 of 6, group 1 being the genes least tolerant of losing a copy. Missense variants: 200 observed, 209.93 expected, observed/expected ratio (o/e) 0.95, 90% interval 0.85 to 1.07. Synonymous variants: 74 observed, 75.09 expected, observed/expected ratio (o/e) 0.99, 90% interval 0.82 to 1.2.
Gene-disease validity (ClinGen):
ClinGen rates the evidence that NDUFAF4 causes each of these diseases.
mitochondrial disease (autosomal recessive): Definitive.
Leigh syndrome (autosomal recessive): Limited. A progressive neurological disease defined by specific neuropathological features associating brainstem and basal ganglia lesions.
Homologues: Orthologues: chimpanzee NDUFAF4 (99% identical), macaque NDUFAF4 (89% identical), pig NDUFAF4 (79% identical), dog NDUFAF4 (78% identical), guinea pig NDUFAF4 (76% identical), mouse Ndufaf4 (72% identical), tropical clawed frog ndufaf4 (53% identical), zebrafish ndufaf4 (44% identical), Drosophila melanogaster CG11722 (34% identical), Caenorhabditis elegans B0035.15 (26% identical).
Diseases named in the same sentence as NDUFAF4 in open-access papers:
NDUFAF4 is named in the same sentence as 9 diseases in open-access papers, as found by Europe PMC text mining. Sharing a sentence is not in itself a finding about the gene and the disease. The quoted sentences say what the papers report.
breast carcinoma (2 papers, 2021 to 2024). "Little is known about its role in cancer, but an earlier report showed that NDUFAF4, also termed HRPAP20, regulates breast cancer cell invasion." (PMID 34281234, 2021).
lung carcinoma (2 papers, 2024 to 2025). "By affecting the expression of hsa-miR-215-5p, the expression of NDUFAF4 can be abnormal, which can impact the lung cancer cells’ migration and apoptosis." (PMID 41154714, 2025). "We concluded that loss of NDUFAF4 is unlikely to be a major contributor to NMTi-induced cell death in (KL/K)MUT lung carcinoma cells." (PMID 38949950, 2024). "siRNA-mediated silencing of NDUFAF4 in NMTi-sensitive lung carcinoma cells caused mitochondrial fragmentation but did not alter cell viability as demonstrated by lack of morphological features of cell death, including DNA fragmentation." (PMID 38949950, 2024).
COVID-19 (1 paper, 2025). A disease caused by infection with severe acute respiratory syndrome coronavirus 2. "Regarding the possible association with COVID-19, recent data show that NDUFAF4 is differentially regulated in the immune cells of patients affected by long COVID in comparison with healthy controls." (PMID 39859996, 2025).
NDUFAF4 also shares sentences with these, for which no sentence is quoted: cancer (2 papers); liver failure (1); malaria (1); neurodegenerative disease (1); ovarian carcinoma (1); Parkinson disease (1).